HAS1 (hyaluronan synthase 1)
Description:
Catalyzes the addition of GlcNAc or GlcUA monosaccharides to the nascent hyaluronan polymer. Therefore, it is essential for the synthesis of hyaluronan, a major component of most extracellular matrices that has a structural role in tissue architecture and regulates cell adhesion, migration and differentiation. This is one of the isozymes catalyzing that reaction. Also able to catalyze the synthesis of chito-oligosaccharide depending on the substrate (By similarity).
Synonyms: HAS
Tractability: Antibody: its Gene Ontology location is reachable by antibodies, with high confidence; UniProt predicts a signal peptide or a membrane-spanning region; the Human Protein Atlas places it where antibodies can reach.
Gene: Protein-coding gene on chromosome 19 (51,713,112 to 51,723,991, reverse strand). Ensembl gene ENSG00000105509.
Subcellular location: Membrane
Subcellular location (Human Protein Atlas): Plasma membrane; Nucleoplasm
Pathways (Reactome):
Metabolism: Hyaluronan metabolism
Gene Ontology:
Molecular function: identical protein binding; protein binding; hyaluronan synthase activity
Biological process: cellular response to platelet-derived growth factor stimulus; hyaluronan biosynthetic process; negative regulation of fibroblast migration; cell adhesion; extracellular matrix assembly; glycosaminoglycan biosynthetic process; polysaccharide biosynthetic process
Cellular component: Golgi apparatus; plasma membrane; UDP-N-acetylglucosamine transferase complex; cytoplasm; membrane
Genetic constraint (gnomAD): Loss-of-function variants: 26 observed, 28.88 expected, observed/expected ratio (o/e) 0.9, 90% interval 0.66 to 1.25. The synonymous counts are far from expectation, so gnomAD's model fits this gene poorly and the ratio says little. Missense variants: 938 observed, 745.33 expected, observed/expected ratio (o/e) 1.26, 90% interval 1.19 to 1.33. Synonymous variants: 408 observed, 338.79 expected, observed/expected ratio (o/e) 1.2, 90% interval 1.11 to 1.31.
Homologues: Orthologues: chimpanzee HAS1 (99% identical), macaque HAS1 (98% identical), mouse Has1 (96% identical), rat Has1 (95% identical), pig HAS1 (95% identical), guinea pig HAS1 (93% identical), dog HAS1 (92% identical). Paralogues in human: HAS3 (53% identical), HAS2 (51% identical).
Diseases named in the same sentence as HAS1 in open-access papers:
HAS1 is named in the same sentence as 108 diseases in open-access papers, as found by Europe PMC text mining. Sharing a sentence is not in itself a finding about the gene and the disease. The quoted sentences say what the papers report.
breast carcinoma (13 papers, 2011 to 2025). "In breast cancer, high HAS1 expression in stromal cells is significantly associated with lymph node metastasis, tumor size, and poor prognosis, findings similar to ours." (PMID 40813707, 2025). "HAS1 is also implicated in the growth and development of breast cancers, as well as the generation of intratumor heterogeneity that maintains a cancer stem cell-like trait or phenotype." (PMID 29137675, 2017). "Recently, HAS1 and HA stainings were found to correlate with each other in breast carcinoma cells of these tumors, and HAS1 was associated with estrogen receptor negativity, HER2 positivity, high relapse rate, and short overall survival." (PMID 25699059, 2015). "In contrast to our qPCR results, it was reported for breast cancer that HAS2 knockdown in Hs578T cancer cells leads to an upregulation of HAS1, HAS3 and HYAL1." (PMID 35767191, 2022). "Surprisingly, HAS1 immunostainings of breast carcinoma cells correlated with hyaluronan staining, estrogen receptor negativity, HER2 positivity, high relapse rate, and short overall survival." (PMID 25699059, 2015). "The minor allele genotypes of HAS1 SNPs are significantly more frequent in MM, WM, CLL and in affected members of a monoclonal gammopathy-prone family than they are in breast cancer, sporadic MGUS or healthy donors." (PMID 24950197, 2014). "The JAK2/STAT3 signaling pathway is preferentially activated in CD44+ breast cancer stem cell population over other cell populations, and hyaluronic acid synthase 1 (HAS1) is a STAT3 signaling-related molecule in basal-like breast cancer." (PMID 23326564, 2013). "HAS1 expression is generally low in normal breast tissue but is upregulated in breast cancer." (PMID 37568628, 2023). "As HAS1 is a prominent prognostic factor in breast cancer and other cancers we sought to determine whether overexpression of HAS1 influences EMT and thereby skew the cellular fate." (PMID 29137675, 2017). "Specifically, HAS1 expression in breast carcinoma cells associated with a high relapse rate and short overall survival, while expression levels of stromal HAS1 and HAS2 were positively related to tumor size and lymph node metastasis." (PMID 26322272, 2015). "Interestingly, immunostainings of tissue sections have demonstrated the role of HAS1 as a poor predictor in breast cancer, and is correlated with high relapse rate and short overall survival." (PMID 25699059, 2015). "However, the precise role of each HAS isoenzyme in breast cancer progression remains unknown; therefore, the identification of HAS1, -2, and -3 specific regulators should be a priority to avoid a general alteration of HA homeostasis." (PMID 37568628, 2023). "In a recent retrospective histological study, authors found that a less favorable outcome of breast carcinoma patients is strongly associated with HAS1 expression (but not HAS2 and HAS3) as seen with shorter overall survival, higher relapse rate, estrogen receptor negativity and HER2 positivity." (PMID 29137675, 2017). "HAS1 SNPs do not associate with breast cancer or ductal carcinoma in situ (DCIS)." (PMID 24950197, 2014). "To determine whether or not the linkage between intronic HAS1 SNPs and risk was restricted to B cell malignancies, we also evaluated a cohort of breast cancer patients." (PMID 24950197, 2014). "The breast cancer cell lines Hs578T and MDA-MB-231 (parental line and a bone-seeking clone) expressed high levels of HAS2 and lower mRNA levels of HAS1 and HAS3." (PMID 36497283, 2022). "Among the compression-upregulated metabolic genes, the expression of ENO2 gene was significantly and positively correlated with COL3A1 and HAS1 genes, whereas PFKFB3 genes were significantly and positively correlated with that of COL1A1, HAS2, and HAS3 genes in breast cancer patient tissues." (PMID 31428701, 2019).
breast carcinoma (continued). "The reliability of the primer of Has2 and HAS1 was confirmed by the positive control cells: Has2 for Lewis lung cell carcinoma cell line, and HAS1 for MDA-MB-231 breast cancer cell line (data not shown)." (PMID 22045192, 2011). "Moreover, the IL-6/STAT3/JAK2 pathway is involved in the maintenance of stem cell–like cancer cells because CD44+CD24+ and CD44+CD24− breast cancer cells have high phospho-STAT3 via their expression of genes such as IL6, PTGIS, and HAS1, which activate an autocrine loop." (PMID 26515594, 2015).
bladder cancer (10 papers, 2014 to 2022). "The association between a high expression of HAS1 with tumor metastasis and poor patient survival has been documented in bladder cancer." (PMID 36232952, 2022). "Similar observations were made in bladder cancer cells in which silencing of HAS1 suppressed the level of CD44 variant isoforms." (PMID 28460475, 2017). "Several alternative splice variants of HAS1 have been reported in Waldenström’s macroglobulinemia, multiple myeloma, and bladder cancer." (PMID 25699059, 2015). "HAS1 has been shown to be prognostic factor in multiple myeloma, colon cancer and bladder cancer and is overexpressed in a variety of other cancers." (PMID 29137675, 2017). "The evaluation of HAS1 and HA expression resulted in a 79% and 88% sensitivity, as well an 83.3% and 100% specificity, respectively, for detecting bladder cancer." (PMID 29207682, 2017). "In bladder cancer, HAS1 has been shown to modulate HA and CD44 levels, affecting tumor growth and progression." (PMID 25699059, 2015). "HAS1 expression is also increased in bladder cancer, correlating with increased hyaluronan levels, and predicting metastasis." (PMID 25699059, 2015). "HAS1 overexpression has also been reported for some solid tumors, including prostate, ovarian and bladder cancers." (PMID 24950197, 2014). "Studies have shown that the overexpresseion of HAS1 in bladder cancer cells can cause an increase in the CD44 variant isoforms (HA receptor), thereby inhibite Fas mediated apoptosis, and promoting the growth and invasion of bladder cancer cells." (PMID 32596162, 2020). "Both full-length and splice variants of HAS1 and RHAMM are overexpressed in multiple myeloma and bladder cancers, but absent in healthy cells." (PMID 29137675, 2017).
multiple myeloma (8 papers, 2013 to 2022). "Altered HAS enzymes function has been implicated in multiple myeloma (HAS1), in renal-controlled fluid balance, heart formation, long bone/spine development, wound healing (HAS2), and seizures (HAS3)." (PMID 26448758, 2015). "Increased expression of HAS1 is associated with poor patient survival in ovarian cancer, colon cancer, Waldenström’s macroglobulinemia, and multiple myeloma." (PMID 25699059, 2015). "Deletions and mutations were introduced into HAS1 minigene constructs to identify regions that can influence aberrant intronic splicing, comparing the splicing pattern in transfectants with that in multiple myeloma (MM) patients." (PMID 23301075, 2013). "In addition, both full length and splice variants of HAS1 are expressed in malignancies like bladder and prostate cancers, multiple myeloma, and malignant mesothelioma." (PMID 25699059, 2015). "The presence of aberrant HAS1 splice variants predicts for poor survival in multiple myeloma (MM)." (PMID 24950197, 2014). "Another previous study demonstrated a higher HAS1 mRNA expression level in bone marrow derived hMSCs suffering from multiple myeloma than in hMSCs from healthy donors." (PMID 32481561, 2020). "In multiple myeloma and Waldenström’s macroglobulinemia, the occurrence of HAS1 splice variants, rather than the full length HAS1, is related to cancer prognosis." (PMID 25699059, 2015). "HAS1 is aberrantly spliced in malignant cells from multiple myeloma (MM) and Waldenstrom macroglobulinemia (WM), but not in their counterparts from healthy donors." (PMID 24950197, 2014).
ovarian carcinoma (8 papers, 2009 to 2025). A malignant neoplasm originating from the surface ovarian epithelium. "Our previous study demonstrates that HA synthesized by HAS1 is associated with tumor neovascularization and predicts tumor aggressiveness and patient survival in ovarian cancer." (PMID 21904555, 2011). "Our results from the Kaplan Meier-Plotter confirm that, indeed, high HAS1 expression leads to lower survival of ovarian cancer patients." (PMID 35767191, 2022). "Following an evaluation of hyaluronan-related gene expression in the ATCC ovarian cancer panel, we studied SKOV3 and SW 626 ovarian cancer cells subjected to HAS2 siRNA or control siRNA treatment in terms of HAS1-3, HYAL2 and HYAL3 mRNA expression." (PMID 35767191, 2022). "Another group demonstrated that HAS1 appears to have an impact on angiogenesis in ovarian cancer, which also negatively correlates with overall survival." (PMID 35767191, 2022). "HAS1 showed reduced gene expression in ovarian cancer tissue with a fold change of 0.11." (PMID 35767191, 2022). "In ovarian cancer patients, high HAS1 levels in ovarian cancer cells but not HAS2 or HAS3 are associated with reduced overall survival." (PMID 21541039, 2011). "We observed significant positive correlations between the expression of hyaluronan synthases (HAS1‐2) and SPHK1 in ovarian cancer patient tissues (TCGA RNAseq and microarray)." (PMID 40356021, 2025). "HAS1, HYAL1 and HYAL4 mRNA expression is significantly upregulated, whereas HAS2, HYAL2 and HYAL3 mRNA expression is significantly downregulated in ovarian cancer tissue compared to controls." (PMID 35767191, 2022). "Of particular relevance, our experiments highlighted that the expression of HAS1 and especially the expression of HAS2 correlates with poorer survival of ovarian cancer patients." (PMID 35767191, 2022). "We analysed a panel of four different ovarian cancer cell lines (i.e., SW 626, SKOV3, Caov-3 and PA-1) and measured the expression levels of several HA-related genes, namely HAS1-3 and HYAL2-3." (PMID 35767191, 2022). "Immunohistochemical stainings confirmed that the levels of HAS1 and HAS3 were relatively low in ovarian cancers, while the signal for HAS2 was more widespread, in line with the real-time RT-PCR-analysis." (PMID 19435493, 2009). "We found that HAS1 and HAS2 expression correlated with worse survival of ovarian cancer patients." (PMID 35767191, 2022). "Our TNMplot analysis of over 700 ovarian cancer specimens revealed that HAS1, HYAL1 and HYAL4 mRNA expression is significantly upregulated, whereas HAS2, HYAL2 and HYAL3 mRNA expression is significantly downregulated in ovarian cancer tissue compared to controls." (PMID 35767191, 2022). "The influence of HAS1 on the survival of ovarian cancer patients has not yet been studied in detail." (PMID 35767191, 2022). "Moreover, high level of HA synthase 1 (HAS1), but not HAS2 and HAS3, is correlated with reduced overall survival in ovarian cancer." (PMID 24739440, 2014).
Waldenstrom macroglobulinemia (6 papers, 2013 to 2025). "The first identified mammalian HAS gene, HAS1, produces a full-length transcript (HAS1-FL) and three variants (HAS1-Va, HAS1-Vb, HAS1-Vc), which are linked to poor survival in malignant myeloma and Waldenström’s macroglobulinemia." (PMID 40507943, 2025). "Besides, some genes are involved in osteoblastogenesis (SEMA3A, BICC1, CHRLD1, and ZNF521) and HAS1 is involved in Waldenstrom’s macroglobulinemia, a post-follicular B-cell lymphoproliferative disorder also associated with M-protein production (IgM)." (PMID 30705326, 2019).
Obesity (5 papers, 2015 to 2025). Accumulation of substantial excess body fat. "In stromal cells of tumors from the same patients, the staining level of HAS1 was related to obesity and large tumor size." (PMID 25699059, 2015). "We observed a statistically significant increase in the circulating levels of HA fragments of LMW in individuals with obesity which were consistent with significant up-regulated expression of the LMW HA synthesizing enzyme hyaluronan synthase-1 (HAS-1) in obese adipose tissue." (PMID 35896710, 2022). "In visceral adipose tissue (VAT) from individuals with obesity, HAS1 is selectively upregulated, while HAS2 and HAS3 remain largely unchanged, suggesting that HAS1-driven HA synthesis in adipose tissue may contribute to systemic inflammation and the development of MASLD." (PMID 41155434, 2025). "The mechanism triggering inflammation in obesity also begins with an upregulation in the expression of LMW-HA-synthesizing enzymes, such as hyaluronan synthase-1 (HAS-1), in obese adipose tissue." (PMID 40723879, 2025). "Regarding HA metabolic turnover, the statistically significant up-regulation of HAS1 in individuals with obesity with no relevant gene expression changes in HAS2 and HAS3 or HA degrading enzymes was confirmed in our previous microarray public data." (PMID 35896710, 2022). "In addition, expression levels of stromal HAS1 and HAS2 were related to obesity, large tumor size, lymph node positivity, and estrogen receptor negativity." (PMID 25699059, 2015). "Genes functionally non-reported in adipose tissue showed a link with a GWAS obesity trait (SLC19A3 and UPK3B genes) and a GWAS blood lipids trait (LVRN, CD300LG, and HAS1 genes)." (PMID 30816281, 2019).
lung carcinoma (4 papers, 2009 to 2021). "In the Lung Cancer dataset, we succeeded in identifying highly discriminative genes (e.g., CALB2, HAS1, and ANXA8) implicated in the pathogenesis of MPM, ADCA, or other tumors." (PMID 19874631, 2009). "Of these, the functions of GSTA1 and HAS1 in lung cancer have been reported, whereas the role of LGI2 in cancer remained unknown." (PMID 32209727, 2020). "However, in agreement with our findings, a negative prognostic role of HAS-1 downregulation in cancer cells has been described in lung cancer and melanoma." (PMID 34066306, 2021). "Moreover, genome-wide transcript analysis of tumor samples confirmed a close correlation between ZEB1 and HAS2 (but not with HAS1 and HAS3) in breast, pancreas and lung cancer specimens (GSE42568, GSE28735 and GSE41271)." (PMID 28086235, 2017).